DERA (deoxyribose-phosphate aldolase)
Description:
Catalyzes a reversible aldol reaction between acetaldehyde and D-glyceraldehyde 3-phosphate to generate 2-deoxy-D-ribose 5-phosphate. Participates in stress granule (SG) assembly. May allow ATP production from extracellular deoxyinosine in conditions of energy deprivation.
Synonyms: CGI-26; DEOC
Tractability: Antibody: its Gene Ontology location is reachable by antibodies, with high confidence. PROTAC: ubiquitination databases record sites on it; its protein half-life has been measured.
Target class: Enzyme; Lyase
Gene: Protein-coding gene on chromosome 12 (15,911,284 to 16,037,381, forward strand). Ensembl gene ENSG00000023697.
Subcellular location: Cytoplasm; Cytoplasmic granule; Nucleus
Subcellular location (Human Protein Atlas): Nucleoplasm
Pathways (Reactome):
Immune System: Neutrophil degranulation
Metabolism: Pentose phosphate pathway
Gene Ontology:
Molecular function: deoxyribose-phosphate aldolase activity; protein binding; lyase activity
Biological process: deoxyribonucleoside catabolic process; pentose-phosphate shunt; deoxyribonucleotide catabolic process; deoxyribose phosphate catabolic process
Cellular component: nucleoplasm; cytosol; extracellular region; ficolin-1-rich granule lumen; secretory granule lumen; cytoplasm; nucleus
Genetic constraint (gnomAD): Loss-of-function variants: 12 observed, 29.57 expected, observed/expected ratio (o/e) 0.41, 90% interval 0.26 to 0.66. The upper end of that interval is the gene's LOEUF score, 0.66, which puts it in group 2 of 6, group 1 being the genes least tolerant of losing a copy. Missense variants: 317 observed, 309.29 expected, observed/expected ratio (o/e) 1.02, 90% interval 0.93 to 1.12. Synonymous variants: 119 observed, 105.51 expected, observed/expected ratio (o/e) 1.13, 90% interval 0.97 to 1.31.
Homologues: Orthologues: chimpanzee DERA (99% identical), macaque DERA (99% identical), pig DERA (96% identical), rabbit DERA (95% identical), dog DERA (94% identical), guinea pig DERA (93% identical), mouse Dera (92% identical), rat Dera (91% identical), zebrafish dera (72% identical), tropical clawed frog dera (56% identical), Drosophila melanogaster Dera (49% identical), Caenorhabditis elegans F09E5.3 (43% identical).
Diseases named in the same sentence as DERA in open-access papers:
DERA is named in the same sentence as 6 diseases in open-access papers, as found by Europe PMC text mining. Sharing a sentence is not in itself a finding about the gene and the disease. The quoted sentences say what the papers report.
thyroid cancer (1 paper, 2021). "Finally, to find prognostic makers of THCA, we performed survival correlation analysis on all genes in samples of thyroid cancer patients, and finally determined five hub genes based on the log-rank value: CD47, CILP, DERA, KLHL33, PSMB8." (PMID 34376710, 2021).
cancer (1 paper, 2016). A tumor composed of atypical neoplastic, often pleomorphic cells that invade other tissues. "UNG, FUCA2, DERA, GMFB, TF, and SNX24 as significantly downregulated upon mir-145 over-expression, are expected to have elevated expressions in tumor samples considering low levels of miR-145 in several cancer types." (PMID 27655328, 2016). "We identified six genes including UNG, FUCA2, DERA, GMFB, TF, and SNX24 as significantly downregulated and two genes including MYL9 and TAGLN as significantly upregulated upon mir-145 over-expression in distinct cancer types." (PMID 27655328, 2016).
DERA also shares sentences with these, for which no sentence is quoted: bladder cancer (1 paper); head and neck squamous cell carcinoma (1); infection (1); tumor (1).